GTF3C4 (general transcription factor IIIC subunit 4)
Description:
Essential for RNA polymerase III to make a number of small nuclear and cytoplasmic RNAs, including 5S RNA, tRNA, and adenovirus-associated (VA) RNA of both cellular and viral origin. Has histone acetyltransferase activity (HAT) with unique specificity for free and nucleosomal H3. May cooperate with GTF3C5 in facilitating the recruitment of TFIIIB and RNA polymerase through direct interactions with BRF1, POLR3C and POLR3F. May be localized close to the A box.
Synonyms: TFIIIC90; KAT12; TF3C-delta; TFIII90; TFIIIC290; TFIIICDELTA
Tractability: PROTAC: UniProt records ubiquitination sites on it; ubiquitination databases record sites on it; its protein half-life has been measured.
Target class: Enzyme; Transferase
Gene: Protein-coding gene on chromosome 9 (132,670,035 to 132,694,953, forward strand). Ensembl gene ENSG00000125484.
Subcellular location: Nucleus
Subcellular location (Human Protein Atlas): Nucleoplasm; Mitochondria
Pathways (Reactome):
Gene expression (Transcription): RNA Polymerase III Abortive And Retractive Initiation; RNA Polymerase III Transcription Initiation From Type 1 Promoter; RNA Polymerase III Transcription Initiation From Type 2 Promoter
Gene Ontology:
Molecular function: histone H3K14 acetyltransferase activity; protein binding; protein-lysine-acetyltransferase activity; RNA polymerase III general transcription initiation factor activity; DNA binding; histone acetyltransferase activity
Biological process: transcription initiation at RNA polymerase III promoter; 5S class rRNA transcription by RNA polymerase III; transcription by RNA polymerase III; tRNA transcription by RNA polymerase III; chromatin remodeling
Cellular component: nucleoplasm; nucleus; transcription factor TFIIIC complex
Genetic constraint (gnomAD): Loss-of-function variants: 21 observed, 60.26 expected, observed/expected ratio (o/e) 0.35, 90% interval 0.25 to 0.5. The upper end of that interval is the gene's LOEUF score, 0.5, which puts it in group 2 of 6, group 1 being the genes least tolerant of losing a copy. Missense variants: 797 observed, 987.09 expected, observed/expected ratio (o/e) 0.81, 90% interval 0.76 to 0.86. Synonymous variants: 388 observed, 374.66 expected, observed/expected ratio (o/e) 1.04, 90% interval 0.95 to 1.13.
Homologues: Orthologues: chimpanzee GTF3C4 (100% identical), macaque GTF3C4 (98% identical), dog GTF3C4 (96% identical), guinea pig GTF3C4 (96% identical), pig GTF3C4 (94% identical), mouse Gtf3c4 (93% identical), rat Gtf3c4 (93% identical), rabbit GTF3C4 (83% identical), tropical clawed frog gtf3c4 (65% identical), zebrafish gtf3c4 (51% identical).
Diseases named in the same sentence as GTF3C4 in open-access papers:
GTF3C4 is named in the same sentence as 4 diseases in open-access papers, as found by Europe PMC text mining. Sharing a sentence is not in itself a finding about the gene and the disease. The quoted sentences say what the papers report.
breast carcinoma (2 papers, 2013 to 2026). "GTF3C4 is overexpressed in breast cancer and associated with poor prognosis." (PMID 41649141, 2026). "Bufalin reduces GTF3C4 protein levels in vivo and in vitro, effectively inhibiting breast cancer progression by suppressing the PI3K/AKT signaling pathway." (PMID 41649141, 2026). "After the knockdown of GTF3C4, the PI3K/AKT signaling pathway is also suppressed, thereby inhibiting the proliferation of breast cancer cells and promoting apoptosis." (PMID 41649141, 2026). "Collectively, this study demonstrates that bufalin targets GTF3C4 to inhibit the PI3K/AKT pathway and remodels the tumor microenvironment, thereby hindering the malignant progression of breast cancer." (PMID 41649141, 2026). "Conversely, within the same cell lines there is a substantial decrease in the HATs GTF3C4 (H3K14ac), MYST1 (H4K16ac) and CDY1 (H4ac), and this is consistent with the observed decrease in H4 acetylation in the MCF7 and MDA-MB231 breast cancer cell lines." (PMID 23826629, 2013).
cancer (2 papers, 2022 to 2024). A tumor composed of atypical neoplastic, often pleomorphic cells that invade other tissues. "GTF3C4, a part of transcription factor in the TFIIIC complex and that is present in the mitochondria and nucleoplasm, is presumed to facilitate enzyme activation and DNA binding, although research on its role in cancer is sparse." (PMID 39175876, 2024).
tumor (2 papers, 2024 to 2026). "We examined the transcriptional levels of key tumor-dependent genes (RUVBL1, GTF3C4, TIGD1, and TAF1A) between groups categorized by MYCN expression levels (low vs. high, n = 30 each) using Q-RT-PCR." (PMID 39175876, 2024).
GTF3C4 also shares sentences with these, for which no sentence is quoted: osteosarcoma (1 paper).